IL2 (interleukin 2)
Diseases named in the same sentence as IL2 in open-access papers (continued):
Sharing a sentence is not in itself a finding about the gene and the disease.
tumor (continued). "Our simulation indicates that suppression of Treg expansion with IL-2 antibody and blockade of PC-Treg and PC-TAM interactions appear to re-activate anti-tumor immune responses and to prevent CRPC occurrence." (PMID 31504033, 2019). "To understand if NFATc3 is a critical factor for cytokines and chemokines known to be involved in tumour growth, we evaluated the impact of nuclear NFATc3 on TNF-α, CXCR-3, GM-CSF, IL-2 and CCL-2 mRNA expression." (PMID 31249342, 2019). "Similarly, adding cytokines that stimulate the immune system such as IFN-a, IL-2, IL-12, IL-10 and the granulocyte-macrophage colony-stimulating factor (GM-CSF) to the treatment regimen or at high concentrations directly into the tumor microenvironment may also alter immune responses." (PMID 35582566, 2019). "The anti-tumor effect achieved by monotherapies (i.e., TKD/IL-2-stimulated NK cells or anti-PD-1 antibodies) that resulted in the delayed tumor progression was shortly abrogated after the discontinuation of the therapies." (PMID 30967859, 2019). "The most attractive solution to overcome resistance due to the tumor microenvironment is to genetically engineer CAR T cells to secrete specific cytokines, such as IL-2 and IL-12." (PMID 31824840, 2019). "Based on the effect of YFTL on splenic lymphocytes and NK cell, the cytokine levels of IL-2, IFN-γ, IL-10, and TGF-β1 in the serum of tumor-bearing mice were detected." (PMID 30781674, 2019). "Our group has established a method to trigger the activity of natural killer (NK) cells by an HSP70 peptide TKD and low dose IL-2 to recognize and kill highly aggressive membrane HSP70 positive tumor cells." (PMID 31652993, 2019). "As tumour infiltrating T cells are often anergic and express immune-checkpoints such as PD-1 and CTLA-4, there will be a paucity of T cell-derived IL2 that will impact upon tumour infiltrating NK cells." (PMID 31595191, 2019). "The IL-2 can promote the proliferation of responsive T cells and IFN-γ play important roles in depressing tumor cell growth and inducing apoptosis of tumor cells." (PMID 30781674, 2019). "Recently, it had been demonstrated that oncolytic adenoviruses express interleukin-2 (IL-2), and the tumor necrosis factor alpha (TNF-a) can achieve an anti-tumor immunomodulatory effect similar to lymphodepletion." (PMID 31781493, 2019). "As a consequence, the activation of NK cells and CD8 cells with stimulation of other cytokines (IL-2 and IFN-γ) have contributed to synergy impact on the inhibition of tumor cells." (PMID 31783838, 2019). "In series of in vitro experiments for analysis of NK cells cytolytic activity toward tumor cells (GL261, A549, LLC) we demonstrated the therapeutic potential of a monotherapy when ex vivo TKD/IL-2-activated NK cells were applied." (PMID 30967859, 2019). "PDX-generated M151002 tumor cells were injected in NOG mice or NOG mice, transgenic for human IL2 (hIL2-NOG)." (PMID 30042422, 2018). "The results shown that combined SEP and αPD-L1 presented significant synergistic antitumor effects, increased the frequency of CD8+ and CD4+ T cells in spleen and tumor, cytotoxic activity of CTL in spleen, and IL-2 and IFN-γ levels in splenocytes and tumor." (PMID 29317734, 2018). "Interleukin-15 (IL-15) exhibits biological activities similar to those of interleukin-2 and enhances the proliferation of CD8+ cytotoxic T cells and natural killer cells, which in turn eliminate tumor cells." (PMID 30150638, 2018). "Taken together, whilst CD11c+ cells from elderly IL-2/CD40-treated mice have increased capacity to present antigens to T cells, their ability to license tumor-specific T cells appears compromised, relative to young counterparts." (PMID 30560130, 2018). "Combination of CAR-T cells with an OV armed with IL-2 and TNF-a was able to control both the primary tumor and tumor metastasis." (PMID 30405639, 2018).
tumor (continued). "In summary, these studies established new concepts for the Ab-based treatment, such as the Ab-IL2, Ab–IFNβ, and Ab–LIGHT fusion proteins, which stimulate or augment the tumor-specific CTL responses to deal with Ab resistance and relapse more effectively." (PMID 30533489, 2018). "Specifically, IL-2/CD40 reduced expression of several regulatory molecules (CD39, A2AR, A2BR, PD-L1, ICOS, and/or IL-10) on young tumor-infiltrating CD11c+ cells and CD4+ T cells, suggesting reduced suppressive activity." (PMID 30560130, 2018). "Following tumour disaggregation using GentleMACS, we initiated TIL cultures by mitogenically stimulating 4 × 106 cells with anti-CD3/anti-CD28 beads and high-dose IL-2." (PMID 30039427, 2018). "A complete schedule of IL-2/CD40 (i.e., 5 doses) was less effective in elderly mice (45% tumor regression), compared to young mice (100% tumor regression)." (PMID 30560130, 2018). "The first prospective trial focusing on the in vivo stimulation of anti-tumor functions by γδ T-cells used the N-BP pamidronic acid, later studies the more potent ZOL in combination with IL-2." (PMID 29725332, 2018). "Stabilization of HIF-1α drives glucose uptake, induces production of S-2-hydroxyglutarate (S-2HG) and consequential epigenetic remodeling as well as increased expression of IL-2, which potentiates CD8+ T cell mediated anti-tumor activity." (PMID 30559740, 2018). "Systemic and local delivery of IL-2 in combination with ACT has been shown to increase CD8+ tumor infiltration and suppression of tumor growth." (PMID 29843822, 2018). "We also examined responses to treatment with intra-tumoral IL-2/anti-CD40 antibody immunotherapy and found it was less effective in elderly (38% tumor regression) compared to young mice (90% regression)." (PMID 30459812, 2018). "(i) The pro-inflammatory cytokines IL-2, TNF, and IFNγ are important for a good T-cell response against the tumor." (PMID 29346301, 2018). "Both αCD137/IL-2-Fc and Lipo-αCD137/Lipo-IL-2-Fc treatment induced substantial CD8+ T-cell and NK cell tumor infiltrates (to comparable levels) and increased intratumoral CD8+/Treg ratios approximately fivefold." (PMID 29295974, 2018). "Many cytokines, like IL-2, IL-15 and IL-21 were chosen to fuse with NKG2D because of their ability to promote immune cell functions and induce anti-tumor responses." (PMID 29316666, 2018). "CTLs activated by derived from tumor-associated antigen HLA-restricted epitopes play a key role in specifically killing cancer cells through directly lysing tumor cells and secrete cytokines such as IFN-γ, TNF-α, and IL-2." (PMID 30596107, 2018). "Tα1-Fc displayed a more effective antitumor activity in the 4T1 and B16F10 tumor xenograft models by upregulating CD86 expression, secreting IFN-γ and IL-2, and increasing the number of tumor-infiltrating CD4+ T and CD8+ T cells." (PMID 30120362, 2018). "IL2 and IL12 as tumor targeted immunocytokines have been tested in combination with tumor irradiation in in vivo models showing promising results." (PMID 30622535, 2018). "Patients received four doses of ipilimumab (3 mg/kg) beginning 2 weeks prior to tumor resection for TIL generation, then 1 week after resection, and 2 and 5 weeks after preconditioning chemotherapy and TIL infusion followed by interleukin-2." (PMID 29552542, 2018). "Cytokines enhancing NK-cell proliferation and function such as IL-2 and IL-15 can be used to potentiate NK cell-mediated ADCC against antibody-coated tumor cells, offering the potential for multiple combinatorial immunotherapy strategies against cancer." (PMID 30294328, 2018). "Functional testing further showed that these Tim3+CD8+ TILs exhibited reduced cell proliferation (Ki67) and cell activity and the production of effector cytokines (IFN-γ, IL-2, and TNF-α), indicating low anti-tumor activity." (PMID 30309387, 2018). "Our previous studies demonstrated that IL-2/CD40 immunotherapy induces complete and permanent tumor regression in young mice." (PMID 30560130, 2018).
tumor (continued). "The expression of serum IL-2 and IFN-γ in model group was notably reduced while TNF-α was notably increased on account of the transplanted tumor (p < 0.05)." (PMID 30966454, 2018). "While PD-L2 expression was detected on both tumor cell lines, albeit with a relatively higher level on HCC827 cells, the effect of PD1-Fc-OX40L on IL-2 secretion appears to correlate with the level of PD-L1 expression on the tumor cells." (PMID 30563566, 2018). "Pro-angiogenic macrophages promote tumor growth and invasion by secreting factors (for example, VEGFA, tumor necrosis factor alpha [TNFα], and interleukin-2 [IL-2]), eventually resulting in resistance to bevacizumab." (PMID 29560266, 2018). "Oncolytic adenoviruses modified to express IL-15 and RANTES or IL-2 and TNF-α have been shown to increase the accumulation and survival of CAR-T cells in the tumor microenvironment." (PMID 30405639, 2018). "This strategy appears to take advantage of complementary differences in temporal killing of tumor cells by effector and memory CD8+ T cells, as well as local paracrine potentiation of effector CD8+ T cell function by memory T cell-secreted IL-2." (PMID 29843822, 2018). "In overnight cytokine release assays in which CAR T cells were challenged with the CD33+ tumor cells HL-60, MOLM-14 and KG-1a, CAR33VH elicited IFN-gamma, TNF-alpha and IL-2." (PMID 30524966, 2018). "To test this idea, we evaluated immunologic changes in the tumor microenvironment following systemic anti-CD137 and IL-2-Fc combination therapy." (PMID 29295974, 2018). "Our results are in agreement with a previous study in which higher expression of IL-2, TNF-α, and granzyme B in CAR T cells was also observed, when similarly made CAR T cells were co-cultured with target tumor cells with EGFR or EGFRvIII." (PMID 29685162, 2018). "B16F10 tumor-bearing mice were administered free or liposomal anti-CD137 and IL-2-Fc combinations four times every other day." (PMID 29295974, 2018). "NHS-IL2 is a fusion protein comprising IL-2, modified to bind high-affinity IL-2 receptors, and a human IgG2 monoclonal antibody (NHS76) targeting DNA from necrotic tumor cells." (PMID 30400835, 2018). "Interleukin-2 (IL-2), interferon-γ (IFN-γ), and tumor necrosis factor-α (TNF-α) levels dose-dependently increased in both serum and ascites from PRP-treated, H22 tumor-bearing mice compared to control mice." (PMID 29735884, 2018). "Therefore, in the lung metastasis model, Lipo-αCD137/IL-2-Fc therapy could eradicate tumors in a fraction of animals when therapy was administered at an early stage and also significantly inhibited tumor growth in the lungs even the therapy was initiated at later stages of tumor progression." (PMID 29295974, 2018). "According to our data, a prolonged incubation of lymphocytes with IL-2 leads to an activation of a subpopulation of CD4+CD25+ cells, which is able to kill HLA-negative tumor cells through the FasL-Fas interaction." (PMID 29850628, 2018). "In preclinical models of NB, the combination of adoptively transferred Vδ2+ T cells (expanded in vitro with ZOL and IL-2) with anti-GD2 antibody ch14.18/CHO and with ZOL significantly suppressed tumor growth as compared to controls." (PMID 30510968, 2018). "NK cells expanded with stimulation with IL-2 and IL-21 in combination with EBV-LCL feeder cells, exhibited cytotoxicity against a variety of tumor targets." (PMID 30517188, 2018). "IL-18 induced the secretion of IFN-γ, IL-2, GM-CSF, TNF-α by the NK cells, and these secreted cytokines exert antitumor effects by directly killing tumor cells or regulating the immune function." (PMID 30002398, 2018). "In terms of tumor cytototxic genes, FASL and CD40L were up-regulated by IL-2 and OKT3; however, TRAIL was down-regulated in mature CIK cells." (PMID 30333226, 2018). "IL-2-mediated stimulation of NK cells and cytotoxic T cells secrete IFN-γ, which further facilitates the infiltration and activation of T cells into the tumor microenvironment." (PMID 29662489, 2018).
tumor (continued). "After 24 h of in vitro restimulation, we predominantly detected CD4+ T cells with a Th1 profile, in both hCT26 tumor-bearing (TB) and tumor-free (TF) vaccinated groups, secreting IFN-γ, IL-2, TNF-α, and GM-CSF." (PMID 30483475, 2018). "In this contemporary report of irAEs associated with high dose IL-2 treatment, the following observations have been made: Overall, patients developing IL-2 related irAEs have significantly improved response (CR + PR) and tumor control (CR + PR + SD) compared to those who did not develop irAEs." (PMID 29254506, 2017). "To investigate if IL-2 was a limiting factor for curative effects of ACT, we labeled MM33 tumor cells with luciferase and transplanted them into hIL2-NOG mice." (PMID 28955032, 2017). "Of note, similar to our previous research with IL-2 and IL-7/15-expanded cells co-cultured with irradiated 4T1 tumor cells, we found that IL-7/15-cultured cells produced less IFN-γ than did the IL-2-cultured T cells." (PMID 28146052, 2017). "The results of our study showed SBE treatment up-regulated Th1 cytokine (IL-2 and IL-12p70) and down-regulated Th17 (IL-17) and Treg (TGF-β and IL-10) related cytokine in the serum of tumor bearing mice." (PMID 28086772, 2017). "The breadth of responses includes anti-tumor effector (Granzyme B, IFN-γ, MIP-1α, TNF-α), stimulatory (GM-CSF, IL-2, IL-8), regulatory (IL-4, IL-13, IL-22), and inflammatory (IL-6, IL-17A) functions." (PMID 29157295, 2017). "In Treg-replete (phosphate-buffered saline-injected) or Treg-depleted (DT injected) tumor-bearing (day 12) DEREG mice, 1:1 mixture of congenic IL-2(CD45.1) and IL-7(CD45.2) effectors was intratumorally injected." (PMID 28496990, 2017). "Employing this approach, they recognized a core of nine cytokines that consistently correlated with efficacious tumour suppression: IL-12p70, IFN-γ, IL-1α, IL-1β, IL-2, IL-3, IL-6, CXCL10, and CXCL9." (PMID 29089667, 2017). "The presence of anti-tumor CD8+ T cells within a tumor can be a positive prognostic factor which correlates with the presence of intratumoral granzyme B, IFN-γ and IL-2, hallmarks of cytolytic CD8+ T cell responses." (PMID 29072624, 2017). "And in nude mice xenograft model, GE11-Ori-Se NPs significantly inhibited the tumor growth via inhibition of tumor angiogenesis by reducing the angiogenesis-marker CD31 and activation of the immune system by enhancing IL-2 and TNF-α production." (PMID 29019267, 2017). "Furthermore, co-administration of E7046 and E7777, an IL-2-diphtheria toxin fusion protein that preferentially kills Tregs, synergistically disrupted the myeloid and Treg immunosuppressive networks, resulting in effective and durable anti-tumor immune responses in mouse tumor models." (PMID 28920002, 2017). "To further investigate mechanism of anti-tumor immune response, we analyzed CD4+ and CD8+ T lymphocyte population and production of INF-γ and IL-2 in spleen." (PMID 29196724, 2017). "For this purpose IL-2/mAb, IL-2WTFc or IL-23XFc treatment was administered in combination with a monoclonal antibody targeting the B16F10 tumour antigen tyrosinase-related protein 1 (TRP-1)." (PMID 28497796, 2017). "The anti-EGFR CAR-T cells secreted cytokines including IL-2, IL-4, IL-6, IFN-γ, TNF-α, GM-CSF, and granzyme B in co-culture with EGFR-positive tumor cells." (PMID 28356156, 2017). "On the contrary, Th1 related cytokine (IL-2, IFN-γ) was significantly up-regulated in the serum of tumor bearing mice (P < 0.01)." (PMID 28086772, 2017). "We also noted a trend of increased expression of IL-2, IL-12 and IL-15 receptors as well as increased phosphorylation of STAT5 in tumor-infiltrating CD8+T-cells following bortezomib treatment." (PMID 28052005, 2017). "Our study showed that both P.y-WT and P.y-GPC3 infection increased high levels of proinflammatory cytokines, such as IL-2, TNF-α and IFN-γ, which leads to activation of defense response effectors against tumor cells." (PMID 28445973, 2017).
tumor (continued). "In different tumor mouse models, T cells expanded by OKT3-28BB RNA electroporation showed anti-tumor activities superior to those of OKT3/IL-2 T cells." (PMID 28523432, 2017). "Inhibition of Smad3 also enhanced anticancer activities of NK cells by increasing releases of granzyme B, IL-2 and IFN-γ locally within the tumour tissues and systemically in the circulation." (PMID 28262747, 2017). "And GE11-Ori-Se NPs was found to significantly inhibit the tumor growth via inhibition of tumor angiogenesis by reducing the angiogenesis-marker CD31 and activation of the immune system by enhancing IL-2 and TNF-α production." (PMID 29019267, 2017). "Due to exhaustion of CD8+ T cells, tumor cells become very aggressive and secrete several pro-inflammatory cytokines, such as tumor necrosis factor alpha (TNF-α), interleukin-2 (IL-2), and interferon gamma (IFN-γ)." (PMID 28878676, 2017). "For example, the cytokine IL-15 exhibits biological activity similar of IL-2 in that it enhances proliferation of CD8+CTL and natural killer (NK) cells, which in turn kill tumor cells." (PMID 29296227, 2017). "Following intervention with IL-2 and CD3, TIL are activated and transformed into tumor-specific lymphocytes or NK." (PMID 29348890, 2017). "High doses of IL-2 and other cytokines stimulate the peripheral blood lymphocytes to transform into LAK, which can kill tumor cells insensitive to NK." (PMID 29348890, 2017). "We did, however, observe significant changes based on tumor status in inflammatory cytokines (IFN-γ, IL-6, IL-5, IL-2, IL-10) and a growth factor (FGF-basic)." (PMID 27893434, 2017). "Following incubation of NK cells with Hsp70 protein or Hsp70–peptide + IL-2, the density of CD94 was found to be upregulated concomitant with an increased cytolytic and migratory activity against membrane Hsp70+ tumor cells." (PMID 27199993, 2016). "Considering the differences in cell characteristics and possibly consequent IL2-GMCSF effects, two concentrations showing significant differences in the cytotoxicity assay against B16F10 cells were applied to other tumor cells." (PMID 26850448, 2016). "iNKT cell-derived cytokines, such as IFNγ and IL-2, are reported to activate cytotoxic T lymphocytes (CTL) and NK cells, which effectively abrogate the actions of tumor cells." (PMID 27631416, 2016). "We also found that liver-derived CD52− NK cells exhibited 4-fold greater cytotoxicity toward K562 tumor cells and produced 20-fold more IFN-γ than liver-derived CD52+ NK cells when activated with IL-2." (PMID 27560943, 2016). "In this present study, we examined new mechanisms contributing to direct B cell-mediated antitumor immunity, including the impact of IL-2, the CXCR4/CXCL12 pathway and perforin in mediating tumor regression after the adoptive transfer of B effector cells." (PMID 27528023, 2016). "The IL-2 mAb S4B6 complex has already been shown to improve NK cell responses and subsequent clearance of tumor cells." (PMID 27821119, 2016). "When LDLN cells from Salmonella-treated mice were exposed to tumor cells, the levels of IFN-γ and TNF increased, whereas the levels of IL-2 decreased with respect to the unexposed culture from the same group." (PMID 26973649, 2016). "Serial imaging shows significant differences in tumor progression between the ‘untreated’ and the ‘PBMC+IL-2 treated’ groups." (PMID 26802025, 2016). "When encountering tumor antigens, these TILs can directly kill tumor cells and release cytokines, such as IFN-γ, IL-2, and TNF, which are known to mediate antitumor immune responses." (PMID 27683579, 2016). "High-dose IL-2 priming amplifies the number of tumor-specific naïve CD8+ T cells without clonal exhaustion and results in the generation of potent tumor-reactive CTLs with capacity to overcome tumor-derived immune suppression." (PMID 27306834, 2016).